AHRR (aryl hydrocarbon receptor repressor)
Diseases named in the same sentence as AHRR in open-access papers (continued):
Sharing a sentence is not in itself a finding about the gene and the disease.
colonic polyps (3 papers, 2021 to 2025). "It remains to be examined if eosinophil-specific AHRR deletion leads to changes in susceptibility of mice to intestinal bacterial infection or the microbiota composition." (PMID 38701199, 2024). "It was previously shown that AhRR expression levels are modestly decreased in precancerous colonic polyps and more profoundly decreased in primary invasive colon carcinomas." (PMID 34778104, 2021).
respiratory diseases (2 papers, 2025). "Previously identified smoking-related CpG sites that were also linked to smoky coal combustion – annotated to genes such as AHRR, SNORD93, NWD1, EDC3, STK24, ZDHHC14, HIF3A – converge on key pathways involved in pollutant response, respiratory diseases, and carcinogenesis." (PMID 40236422, 2025).
AHRR also shares sentences with these, for which no sentence is quoted: Angiofibroma (2 papers); autism (2); Hypertension (2); metabolic disease (2); squamous cell carcinoma (2); adenocarcinoma (1); adenoma (1); childhood asthma (1); chromophobe renal cell carcinoma (1); Cirrhosis (1); Crohn disease (1); depression (1); glioma (1); heart failure (1); helminth infection (1); hemangiopericytoma (1); hematopoietic cancers (1); infection (1); inflammatory bowel disease (1); influenza (1); intestinal bacterial infection (1); kidney tumors (1); liver cancer (1); lymphoblastic leukemia (1); metastatic disease (1); oral squamous cell carcinoma (1); pneumonia (1); prostate carcinoma (1); psychiatric diseases (1); sarcoma (1).
A further 5 diseases each share a sentence with AHRR in 1 paper.